OTUB2 (OTU deubiquitinase, ubiquitin aldehyde binding 2)
Diseases named in the same sentence as OTUB2 in open-access papers (continued):
Sharing a sentence is not in itself a finding about the gene and the disease.
atherosclerosis (1 paper, 2025). A disease characterized by the build-up of fatty material and calcium deposition in the arterial wall resulting in partial or complete occlusion of the arterial lumen. "Additionally, Otubain-1 (OTUB1) and OTUB2 belong to the same subfamily, which was previously reported to play important roles in the regulation of bone homeostasis and atherosclerosis 30-31." (PMID 39776804, 2025).
calcification (1 paper, 2025). Process by which organic tissue becomes hardened by the physiologic deposit of calcium salts. "VSMC-specific OTUB2 overexpression caused more severe aortic calcification in CKD mice." (PMID 39776804, 2025).
cerebral infarction (1 paper, 2025). An ischemic condition of the brain, producing a persistent focal neurological deficit in the area of distribution of the cerebral arteries. "Here, we found that deletion of the deubiquitinating enzyme Otubain-2 (OTUB2) significantly alleviated ischemia-induced cerebral infarction and neurological deficits, accompanied by a reduction in neuronal loss, glial activation, and neuroinflammation." (PMID 40021931, 2025).
colitis (1 paper, 2024). Inflammation of the colon. "MDP administration significantly ameliorated colitis in Otub2+/+ mice with a concomitant reduction in body weight loss, disease activity and colon shortening." (PMID 39358938, 2024). "In this study, we found that ablation of OTUB2 aggravated DSS‐induced experimental colitis and OTUB2 alleviated colonic inflammation mainly by regulating haematopoietic cells." (PMID 39358938, 2024). "In this report, we demonstrated that OTUB2 ameliorated colitis, providing novel insights into the pathophysiological function of OTUB2." (PMID 39358938, 2024). "Consistently, higher levels of pro‐inflammatory Il1b, Il6, Tnf, Cxcl2 and Cxcl10 mRNA were detected in the colon of Otub2–/– mice, further consolidating the more severe colitis in these mice." (PMID 39358938, 2024). "Collectively, these data show that deletion of OTUB2 exacerbates experimental colitis in mice, indicative of a protective role of OTUB2 in intestinal inflammation." (PMID 39358938, 2024). "To explore the role of OTUB2 in intestinal inflammation, we induced experimental colitis in Otub2+/+ and Otub2–/– mice with DSS." (PMID 39358938, 2024). "PAS/AB staining also revealed that Otub2–/– mice lost more goblet cells than did Otub2+/+ mice during experimental colitis." (PMID 39358938, 2024). "Colitis was significantly aggravated in Otub2–/– mice and bone marrow chimeric mice receiving Otub2–/– bone marrow." (PMID 39358938, 2024). "Together, these findings show that the expression of OTUB2 in haematopoietic cells plays a critical role in suppressing colonic inflammation, implying that OTUB2 ameliorates colitis by regulating leukocytes." (PMID 39358938, 2024). "In addition to DSS‐induced colitis, OTUB2 ablation also exacerbated experimental colitis induced by TNBS." (PMID 39358938, 2024). "Given that intestinal epithelial cells (IECs) form the critical intestinal barrier that segregates intestinal microbes and IECs undergo programmed cell death during colitis, OTUB2 may affect experimental colitis by regulating IECs." (PMID 39358938, 2024). "To confirm whether OTUB2 exerts its function in colitis by regulating IECs or immune cells, we constructed bone marrow chimeric mice by reconstituting irradiated Otub2+/+ mice with bone marrow from Otub2+/+ or Otub2–/– mice." (PMID 39358938, 2024). "Irradiated Otub2+/+ mice receiving Otub2–/– bone marrow (KO → WT) were more sensitive to DSS‐induced experimental colitis than irradiated Otub2+/+ mice reconstituted with Otub2+/+ bone marrow (WT → WT), as shown by the increased body weight loss and disease activity in KO → WT mice." (PMID 39358938, 2024). "In mice, OTUB2 ablation abolished the protective effects of MDP administration in colitis." (PMID 39358938, 2024). "In aggregate, these results demonstrate that OTUB2 promotes MDP‐induced innate immune responses in macrophages, indicating that OTUB2 ameliorates colitis by bolstering NOD2‐mediated protective effects in macrophages." (PMID 39358938, 2024). "To study the function of OTUB2 in IBD, we generated Otub2–/– mice and treated them with dextran sulfate sodium (DSS) to induce experimental colitis." (PMID 39358938, 2024). "OTUB2 was highly expressed in colon‐infiltrating macrophages in both humans with IBD and mice with DSS‐induced experimental colitis." (PMID 39358938, 2024). "However, these protective effects of MDP were absent in Otub2–/– mice, indicating that OTUB2 is essential for NOD2‐mediated protective effects in colitis." (PMID 39358938, 2024).
diffuse large B-cell lymphoma (1 paper, 2025). "Consistent with this, analogous phenomena were observed in OTUB2 in NSCLC and OTUD3 in diffuse large B-cell lymphoma (DLBCL)." (PMID 40469292, 2025).
esophageal cancer (1 paper, 2022). A primary or metastatic malignant neoplasm involving the esophagus. "Bioinformatics analysis revealed OTUB2 was highly expressed in esophageal cancer and was associated with YAP1/TAZ." (PMID 35850645, 2022). "Bioinformatics analysis was used to analyze OTUB2 expression in esophageal carcinoma and interactions between OTUB2 and YAP1/TAZ." (PMID 35850645, 2022). "Following TIMER and GEPIA database analysis OTUB2 expression in various tumors, revealed that OTUB2 was highly expressed in various tumor tissues, and the expression in esophageal cancer tissues was significantly higher than that in normal esophageal epithelial tissues." (PMID 35850645, 2022).
glioma (1 paper, 2025). A benign or malignant brain and spinal cord tumor that arises from glial cells (astrocytes, oligodendrocytes, ependymal cells). "For instance, OTUB1 in glioma, CRC, GC, and HCC; OTUB2 in BC; OTUD2 in NSCLC; TNFAIP3 in BC and ESCC." (PMID 40469292, 2025).
ovarian carcinoma (1 paper, 2025). A malignant neoplasm originating from the surface ovarian epithelium. "The epigenetic silencing of Otubain 2 (OTUB2) promotes mitochondrial metabolic reprogramming and drug resistance in ovarian cancer." (PMID 40438494, 2025).
thyroid cancer (1 paper, 2022). "One is precisely targeting upstream molecules that can regulate the expression of OTUB2, such as miR-29a-3p in thyroid cancer." (PMID 35309903, 2022).
type 1 diabetes (1 paper, 2021). "Meanwhile, Otub2 has been shown to act through the inhibition of NF-κB signaling in type 1 diabetes." (PMID 34022799, 2021).
viral infection (1 paper, 2014). "We first screened the reported deubiquitinases for TRAF3 and found that HSCARG interacted with OTUB1 more potently than OTUB2, UCHL1, OTUD7B, and USP25, and this interaction was enhanced by viral infection." (PMID 24763515, 2014).
tumor (22 papers, 2013 to 2026). "Our results indicated that OTUB2-KO tumor cells were significantly more susceptible to killing by OT-1 CTLs than were control cells." (PMID 38167274, 2024). "In NSCLC, OTUB2 (OTU deubiquitinase, ubiquitin aldehyde binding 2) was significantly upregulated in primary tissues and associated with tumor malignancy." (PMID 35307036, 2022). "OTUB2 can be used as a tumor stem cell and metastasis promoting factor, and is associated with the progression of different tumors." (PMID 35850645, 2022). "Moreover, we compared PD-L1 and OTUB2 expression in a panel of human tumor cell lines, and found that PD-L1 expression was positively associated with OTUB2 abundance." (PMID 38167274, 2024). "We further examined the effect of OTUB2 deficiency on the total PD-L1 level in tumor cells." (PMID 38167274, 2024). "Whereas OTUB2 acted as a tumor suppressor in OV, mechanistically, OTUB2 silencing destabilized SNX29P2, which subsequently prevented the degradation of HIF-1α." (PMID 40469292, 2025). "We next investigated the molecular mechanism by which OTUB2 is involved in the regulation of the tumor-specific immune response." (PMID 38167274, 2024). "Our in vitro and in vivo data demonstrate that OTUB2 functions as a negative regulator of T-lymphocyte-mediated antitumor immunity by modulating PD-L1 stabilization on tumor cells and thereby promotes tumor immune evasion." (PMID 38167274, 2024). "This rescue experiment indicates that OTUB2-IN-1 attenuates tumor growth through regulation of PD-L1." (PMID 38167274, 2024). "In summary, we demonstrated a general mechanism of immunosuppression in tumor cells mediated through OTUB2-mediated stabilization of PD-L1." (PMID 38167274, 2024). "More importantly, orally-administered phosphatidylserine impairs tumor initiation of OTUB2-low ESCC cells in mouse models, making phosphatidylserine administration as a potential anti-ESCC strategy." (PMID 38989149, 2024). "Analogous phenotypic differences in tumor growth were also observed between WT and OTUB2-KO mouse LL/2 and B16-F10 cells." (PMID 38167274, 2024). "Given that PD-L1 upregulation can lead to immunosuppression via inhibition of CTLs, we then determined the effect of OTUB2 KO on the CTL-mediated killing of tumor cells by using an OT-1 transgenic mouse model." (PMID 38167274, 2024). "Eliminating OTUB2 significantly reduced PD-L1 protein levels on tumor cells, enhancing their vulnerability to the cytotoxic effects of CD8+ T cells." (PMID 38638430, 2024). "Here we identify tumor-cell-expressed otubain-2 (OTUB2) as a negative regulator of antitumor immunity, acting through the PD-1/PD-L1 axis in various human cancers." (PMID 38167274, 2024). "Taken together, these data identify OTUB2 as a specific positive regulator of PD-L1 in different tumor cells." (PMID 38167274, 2024). "Knocking down OTUB2 reduced MC38 tumor growth and overall survival in immunocompetent C57BL/6J mice." (PMID 38167274, 2024). "The cycloheximide (CHX)-chase experiment demonstrated faster degradation of PD-L1 protein in OTUB2-KD tumor cells and slower degradation of PD-L1 protein in OTUB2-overexpressing cells." (PMID 38167274, 2024). "In summary, OTUB2‐IN‐1 exhibits significant antitumor potential by precisely targeting DUBs to regulate tumor immune escape mechanisms." (PMID 39678489, 2024). "Genetic deletion of OTUB2 markedly decreases the expression of PD-L1 proteins on the tumor cell surface, resulting in increased tumor cell sensitivity to CD8+ T-cell-mediated cytotoxicity." (PMID 38167274, 2024). "On the structural basis of the binding pocket of OTUB2, we identify OTUB2-IN-1, a specific inhibitor of OTUB2, which can reduce the expression of PD-L1 proteins in tumor cells and suppress tumor growth by promoting robust intra-tumoral infiltration of CTLs." (PMID 38167274, 2024). "In the present study, we show that OTUB2 is a key regulator of PD-L1 in a broad range of tumor cells." (PMID 38167274, 2024).
tumor (continued). "In ESCC, DNA hypermethylation of otubain 2 (OTUB2) has been found to induce tumor initiation and chemoresistance by regulating biosynthesis of phosphatidylserine." (PMID 38989149, 2024). "We found that the number of activated T cells was significantly increased in a coculture of OT-1 T cells and OTUB2-KO LL/2 tumor cells compared with a coculture of OT-1 cells and control tumor cells." (PMID 38167274, 2024). "We also demonstrated that PD-L1 downregulation by depletion of OTUB2 resulted in inhibition of tumor growth by promoting robust intratumoral infiltration of CTLs." (PMID 38167274, 2024). "To assess the immunoregulatory effect of OTUB2 on tumor growth in syngeneic mouse models, we first knocked down OTUB2 expression in mouse MC38 cells using short hairpin RNA (shRNA)." (PMID 38167274, 2024). "As expected, in comparison to the control group, overexpressed PD-L1 resulted in a substantial increase of tumor growth, whereas OTUB2-IN-1 significantly reduced the PD-L1-overexpressing tumor growth." (PMID 38167274, 2024). "In the mouse LL/2 tumor model, OTUB2‐IN‐1 treatment significantly inhibited tumor growth, prolonged mouse survival, and exhibited no significant toxicity." (PMID 39678489, 2024). "Together, these results reveal the roles of OTUB2 in PD-L1 regulation and tumor evasion and lays down the proof of principle for OTUB2 targeting as therapeutic strategy for cancer treatment." (PMID 38167274, 2024). "OTUB2 is a dihydroubiquitase, a member of the ovarian tumor domain (OTU) family with effects on various biological activities of the body." (PMID 35850645, 2022). "OTUB2, a deubiquitinase, regulates tumor progression by deubiquitinating substrate proteins." (PMID 41986305, 2026). "In vivo, the knockdown of OTUB2 significantly inhibited tumor growth in a xenograft mouse model." (PMID 41857621, 2026). "The subcutaneous xenograft model showed that OTUB2 knockdown suppressed tumor growth in vivo." (PMID 40296903, 2025). "Gene set enrichment analysis (GSEA) suggested that OTUB2 may be involved in tumor proliferation and metastasis." (PMID 40296903, 2025). "We further evaluated the therapeutic potential of OTUB2-IN-1 using a mouse LL/2 tumor model." (PMID 38167274, 2024). "Significantly reduced PD-L1 staining was observed in OTUB2-KO tumor cells." (PMID 38167274, 2024). "Furthermore, we found that the addition of eeyarestatin I (Eer I), a specific inhibitor of ERAD, rescued PD-L1 levels in both OTUB2-KD human tumor cells and OTUB2-KO mouse tumor cells." (PMID 38167274, 2024). "Given the important role of OTUB2-mediated PD-L1 stability in suppression of tumor growth, we reasoned that targeting OTUB2 could be beneficial in the treatment of cancer." (PMID 38167274, 2024). "Our results provide a new notion that OTUB2 is an immune regulator that targets and inhibits PD-L1 degradation, consequently leading to the promotion of T-lymphocyte-mediated antitumor immunity and suppression of tumor growth." (PMID 38167274, 2024). "OTUB2 plays a key role in regulating PD-L1 expression and tumor immune evasion." (PMID 38638430, 2024). "Analysis of bulk tumor gene expression data from TCGA revealed a significant negative correlation between the genes encoding OTUB2 and intratumoral T-cell abundance (CD3E and CD8A) in multiple cancer types." (PMID 38167274, 2024). "Furthermore, depleting CD8+ T cells with anti-CD8 antibodies reversed this OTUB2-KD-induced MC38 tumor growth inhibition in C57BL/6J mice, which functionally implicates CD8+ T cells in the OTUB2-KD tumor phenotype." (PMID 38167274, 2024). "Collectively, these analyses indicate that the intratumoral CD8+ CTL abundance is increased in cancer tissues with a low OTUB2 level, suggesting that OTUB2 may be involved in the regulation of the tumor-specific immune response." (PMID 38167274, 2024). "An OTUB2 inhibitor effectively diminished PD-L1 levels and inhibited tumor growth." (PMID 38638430, 2024).
tumor (continued). "These authors found that OTUB2 could directly act on YAP1/TAZ independently of the Hippo signaling pathway to promote tumor proliferation." (PMID 35850645, 2022). "Whether OTUB2 protects tumor cells through immunosuppression and thus deteriorates tumor progression will be a new research direction." (PMID 35309903, 2022). "However, there are relatively few studies on OTUB2, and our understanding of its role in tumor progression is limited, especially in GC." (PMID 35110531, 2022). "OTUB2 is a deubiquitinating enzyme that contributes to tumor progression." (PMID 35110531, 2022). "The findings suggest that OTUB2 may act as a tumor promoter in the carcinogenesis of TNBC." (PMID 40296903, 2025). "Furthermore, we also performed T-cell cytotoxicity assays to confirm that the immune-inhibitory function of PD-L1 was affected by OTUB2 in human tumor cells, OTUB2 KD rendered tumor cells more sensitive to human peripheral blood mononuclear cell (PBMC)-mediated killing." (PMID 38167274, 2024). "CONCLUSIONS: We conclude that OTUB2 deubiquitinates and stabilizes EIF4A3 to promote TNBC progression via TPI1-mediated glycolysis of tumor cells." (PMID 41857621, 2026). "CONCLUSION: CAF-exo circ_0067557 promotes EMT, invasion, metastasis, and tumor progression in CRC by recruiting BHLHE40 and activating OTUB2 transcription." (PMID 42115880, 2026). "In vivo experiments further confirmed that circ_0067557 markedly enhanced tumor growth and distant metastasis through the BHLHE40/OTUB2 signaling axis." (PMID 42115880, 2026). "Taken together, these complementary assays provide strong evidence that OTUB2 plays a critical role in enhancing the migratory and invasive abilities of TNBC cells, which are key processes in tumor migration." (PMID 40296903, 2025). "Subsequent animal model experiments and immunohistochemical analysis showed that OTUB2‐IN‐1 also demonstrated therapeutic potential in mouse B16‐F10 and KLN205 tumor models." (PMID 39678489, 2024). "Thus, the question of whether OTUB2 also plays a tumor-promoting role in ESCC has also been raised." (PMID 35850645, 2022). "For instance, significantly upregulated OTUB2 in NSCLC stimulated the Warburg effect and was closely related to metastasis, advanced tumor stages, poor survival, and recurrence." (PMID 33403045, 2021). "When wild-type (WT, Control) and OTUB2-knockout (KO) MC38 cells were inoculated parallel into syngeneic and immunodeficient mice, knocking out OTUB2 reduced MC38 tumor growth in immunocompetent C57BL/6J mice but not in immunodeficient BALB/c-nude mice." (PMID 38167274, 2024). "An inhibitor of OTUB2, interfering with its deubiquitinase activity without disrupting the OTUB2-PD-L1 interaction, successfully reduces PD-L1 expression in tumor cells and suppressed tumor growth." (PMID 38167274, 2024). "Additionally, tumor infiltration of CD8 and GZMB CTLs was significantly increased in OTUB2‐IN‐1‐treated mouse tumors, while the expression of PD‐L1 was significantly reduced." (PMID 39678489, 2024). "In contrast, overexpression (OE) of OTUB2 in B16-F10 cells did not alter the in vitro growth rate of tumor cells but promoted tumor growth in C57BL/6J mice." (PMID 38167274, 2024). "OTUB2-IN-1 treatment significantly suppressed tumor growth and prolonged mouse survival, and no obvious toxicity was observed." (PMID 38167274, 2024). "When OTUB2 is overexpressed, it can directly stabilize and bind to YAP1/TAZ through SUMO, activate the YAP1/TAZ expression and activating downstream target genes such as CTGF and CYR61 to promote the proliferation, invasion and metastasis of tumor cells." (PMID 35850645, 2022). "Additionally, while our findings suggest that OTUB2 promotes TNBC cell migration, this conclusion is based solely on in vitro assays, and we lack in vivo metastasis models to further validate its role in tumor dissemination." (PMID 40296903, 2025). "Furthermore, 10 μM OTUB2-IN-1 exhibited no obvious inhibitory effect on the viability of tumor cells." (PMID 38167274, 2024).
tumor (continued). "Additionally, although OTUB2 potentially modulates the functions of multiple cellular proteins involved in diverse functions, the other posttranslational regulatory targets of OTUB2 in tumor cells have not yet been elaborated." (PMID 38167274, 2024). "OTUB2 could make a binding relationship and deubiquitination, thereby stabilizing YAP and TAZ to activate the Hippo pathway, stimulate cancer stem cell characteristics, and maintain tumor cell proliferation and metastasis." (PMID 38819228, 2024). "However, the cancer-promoting effect of OTUB2 has been widely known, there is no report on the relationship between OTUB2 and tumor immunity." (PMID 35309903, 2022).